PTPN22 (protein tyrosine phosphatase non-receptor type 22)
Description:
Acts as a negative regulator of T-cell receptor (TCR) signaling by direct dephosphorylation of the Src family kinases LCK and FYN, ITAMs of the TCRz/CD3 complex, as well as ZAP70, VAV, VCP and other key signaling molecules. Associates with and probably dephosphorylates CBL. Dephosphorylates LCK at its activating 'Tyr-394' residue. Dephosphorylates ZAP70 at its activating 'Tyr-493' residue. Dephosphorylates the immune system activator SKAP2. Positively regulates toll-like receptor (TLR)-induced type 1 interferon production. Promotes host antiviral responses mediated by type 1 interferon (By similarity). Regulates NOD2-induced pro-inflammatory cytokine secretion and autophagy. Acts as an activator of NLRP3 inflammasome assembly by mediating dephosphorylation of 'Tyr-861' of NLRP3. Dephosphorylates phospho-anandamide (p-AEA), an endocannabinoid to anandamide (also called N-arachidonoylethanolamide) (By similarity).
Synonyms: LyP; PEP; PTPN8; Lyp1; Lyp2; PTPN22.5; PTPN22.6
Tractability: Small molecule: a structure with a bound ligand is known; a high-quality ligand is known; it has a binding pocket of medium quality; it belongs to a druggable protein family. PROTAC: ubiquitination databases record sites on it; its protein half-life has been measured; a small molecule that binds it is known.
Target class: Tyrosine protein phosphatase; Enzyme; Phosphatase; Protein Phosphatase
Gene: Protein-coding gene on chromosome 1 (113,813,811 to 113,871,753, reverse strand). Ensembl gene ENSG00000134242.
Subcellular location: Cytoplasm
Subcellular location (Human Protein Atlas): Nucleoplasm; Plasma membrane; Vesicles
Pathways (Reactome):
Immune System: Phosphorylation of CD3 and TCR zeta chains; Translocation of ZAP-70 to Immunological synapse
Gene Ontology:
Molecular function: phosphatase activity; protein binding; protein tyrosine phosphatase activity; ubiquitin protein ligase binding; kinase binding; SH3 domain binding; non-membrane spanning protein tyrosine phosphatase activity; phosphoprotein phosphatase activity
Biological process: cellular response to muramyl dipeptide; lipopolysaccharide-mediated signaling pathway; negative regulation of autophagy; negative regulation of gene expression; negative regulation of interleukin-6 production; negative regulation of interleukin-8 production; negative regulation of JUN kinase activity; negative regulation of nucleotide-binding oligomerization domain containing 2 signaling pathway; negative regulation of p38MAPK cascade; negative regulation of T cell activation; negative regulation of T cell receptor signaling pathway; negative regulation of tumor necrosis factor production; positive regulation of ERK1 and ERK2 cascade; positive regulation of gene expression; positive regulation of NLRP3 inflammasome complex assembly; positive regulation of protein K63-linked ubiquitination; positive regulation of toll-like receptor 3 signaling pathway; positive regulation of toll-like receptor 4 signaling pathway; positive regulation of type I interferon production; positive regulation of type II interferon production; regulation of natural killer cell proliferation; regulation of non-canonical NF-kappaB signal transduction; response to lipopolysaccharide; phosphoanandamide dephosphorylation; regulation of B cell receptor signaling pathway; and 4 more
Cellular component: cytoplasm; cytoplasmic side of plasma membrane; nucleus; perinuclear region of cytoplasm; cytosol
Genetic constraint (gnomAD): Loss-of-function variants: 55 observed, 72.97 expected, observed/expected ratio (o/e) 0.75, 90% interval 0.61 to 0.94. The upper end of that interval is the gene's LOEUF score, 0.94, which puts it in group 4 of 6, group 1 being the genes least tolerant of losing a copy. Missense variants: 692 observed, 786.9 expected, observed/expected ratio (o/e) 0.88, 90% interval 0.82 to 0.94. Synonymous variants: 270 observed, 270.21 expected, observed/expected ratio (o/e) 1, 90% interval 0.9 to 1.11.
Homologues: Orthologues: chimpanzee PTPN22 (99% identical), macaque PTPN22 (94% identical), rabbit PTPN22 (78% identical), dog PTPN22 (78% identical), pig PTPN22 (77% identical), mouse Ptpn22 (71% identical), rat Ptpn22 (69% identical), tropical clawed frog PTPN22 (41% identical). Paralogues in human: PTPN12 (34% identical), PTPN18 (21% identical), PTPRG (16% identical), PTPRF (16% identical), PTPRC (15% identical), PTPRZ1 (15% identical), PTPRK (15% identical), PTPRS (15% identical), PTPRT (15% identical), PTPRD (15% identical), PTPRA (15% identical), PTPRE (15% identical), and 23 more.
Diseases named in the same sentence as PTPN22 in open-access papers:
PTPN22 is named in the same sentence as 183 diseases in open-access papers, as found by Europe PMC text mining. Sharing a sentence is not in itself a finding about the gene and the disease. The quoted sentences say what the papers report.
autoimmune disease (210 papers, 2005 to 2026). A disorder resulting from loss of function or tissue destruction of an organ or multiple organs, arising from humoral or cellular immune responses of the individual to their own tissue constituents. "PTPN22 is associated with various autoimmune diseases, including rheumatoid arthritis and systemic lupus erythematosus, due to its role in T-cell signaling dysregulation." (PMID 39860439, 2025). "The PTPN22 alternative allele, 1858C>T, is expressed in 5% to 15% of the North American population and is strongly associated with the development of autoimmune disease while simultaneously capable of providing protection during viral infection and cancer." (PMID 41208109, 2025). "The generational persistence of this PTPN22 allele, despite its strong association with various severe autoimmune diseases, poses an evolutionary paradox." (PMID 40791464, 2025). "Despite the strong genetic link between the minor allele of PTPN22 and the development of various autoimmune diseases, this allele persists in the human population." (PMID 40791464, 2025). "Subsequently, a 2006 meta-analysis by Lee linked the PTPN22 SNP to autoimmune diseases such as rheumatoid arthritis, systemic lupus erythematosus, Graves’ disease, T1D, and juvenile idiopathic arthritis." (PMID 40238817, 2025). "Two SNPs at the PTPN22 gene locus have been strongly associated with several autoimmune diseases, and their contribution to disease risk is context-dependent." (PMID 39944077, 2025). "PTPN22 (Protein Tyrosine Phosphatase Non-Receptor Type 22), a well-known immune regulator, has been implicated in autoimmune disease and inflammation." (PMID 41299637, 2025). "The PTPN22 gene plays a crucial role in regulating immune responses, and variations within this gene have been implicated in the development of various autoimmune diseases." (PMID 39796280, 2025). "We previously implemented a novel immunotherapy, employing siRNA directed against the C1858T variant of PTPN22 delivered via functionalized lipoplexes, in order to halt autoimmune disease progression." (PMID 40574023, 2025). "Variants in the PTPN22 gene have been linked to an elevated risk of various autoimmune diseases, including T1D." (PMID 40238817, 2025). "PTPN22 has attracted a great deal of interest over the past two decades due to the strong association of SNPs with autoimmune disease and its role as a key regulator of T cell and other leukocyte responses." (PMID 39039893, 2024). "Of note, single nucleotide polymorphisms (SNPs) in PTPN22 have been identified as risk factors for the development of autoimmune diseases." (PMID 39039893, 2024). "In this study, we examine gene expression and function of immune cell subsets to demonstrate how a common allelic variant of PTPN22, which strongly increases the risk of autoimmune disease, promotes successful clearance of an otherwise chronic viral infection." (PMID 38512979, 2024). "The 1858C>T allele of the tyrosine phosphatase PTPN22 is present in 5–10% of the North American population and is strongly associated with numerous autoimmune diseases." (PMID 38512979, 2024). "The human protein, PTPN22, has been studied extensively within the context of the adaptive immune system and mutations that affect PTPN22 function are implicated in multiple autoimmune disorders." (PMID 39173071, 2024). "This is especially pertinent given the well-documented association between PTPN22 polymorphisms and various autoimmune diseases." (PMID 39451542, 2024). "Polymorphisms in the PTPN22 gene, specifically the +1858C/T variant, are associated with various autoimmune diseases, suggesting a potential connection to obesity." (PMID 39594522, 2024). "Similar results were reported for knock-in mice that express the autoimmune disease-associated PTPN22 R619W (equivalent to human R620W) variant." (PMID 38334623, 2024).
autoimmune disease (continued). "rs2488457 (−1123 G>C), rs33996649 (+788 G>A) and rs2476601 (+1858 C>T) are functional polymorphisms of the PTPN22 gene associated with multiple inflammatory conditions, including autoimmune disorders such as pSS." (PMID 36900045, 2023). "This study uncovers novel interactions between two independent autoimmune risk loci, UBASH3A and PTPN22, each of which contribute to multiple distinct autoimmune diseases." (PMID 37240014, 2023). "Lymphoid tyrosine phosphatase (LYP) encoded by the gene PTPN22 has been found to increase the risk of many autoimmune diseases." (PMID 37771457, 2023). "Many autoimmune diseases, including type 1 diabetes, arthritis, systemic lupus and vitiligo, have also been previously associated with PTPN22 variants." (PMID 37239478, 2023). "CD4 T cells were chosen for this study based on well-documented use in gene editing models and likely key roles in PTPN22 associated autoimmune diseases." (PMID 36961507, 2023). "An arginine to tryptophan substitution (R620W) resulting from a single nucleotide polymorphism (SNP; rs2476601) within PTPN22 is broadly associated with a large number of autoimmune diseases." (PMID 36961507, 2023). "Multiple single-nucleotide polymorphisms (SNPs) in the PTPN22 gene have been associated with susceptibility to autoimmune diseases." (PMID 36900045, 2023). "On the other hand, murine model studies have demonstrated that PTPN22 loss of function in myeloid cells results in an augmented inflammatory effector phase of autoimmune disease and GC generation by influencing the number and activity of Th follicular cells." (PMID 36900045, 2023). "Diverse case-control studies have examined the potential contribution of PTPN22 SNPs and their haplotypes to susceptibility to different autoimmune diseases (AIDs); however, results are inconsistent, in part because of ethnic and racial differences." (PMID 36900045, 2023). "The R620W variant of PTPN22 has been associated with an increased risk of several autoimmune diseases, amongst them diabetes, rheumatoid arthritis, and systemic lupus erythematosus." (PMID 35587260, 2022). "PTPN22 is a major autoimmune risk locus: the R620W gain-of-function allele is found at high frequencies in patients with autoimmune disease, including T1D, RA, and SLE." (PMID 36359789, 2022). "PTPN22, a negative regulator of T cell activation, has been associated with the development of multiple autoimmune diseases, including SLE, rheumatoid arthritis, type 1 diabetes, and autoimmune thyroid disease." (PMID 35784356, 2022). "PTPN22 has been confirmed to be associated with a variety of autoimmune diseases, including type I diabetes, rheumatoid arthritis and systemic lupus erythematosus." (PMID 35692826, 2022). "Among them, the PTPN22 (protein tyrosine phosphatase non-receptor type 22) gene is a susceptibility allele for some autoimmune diseases including MG." (PMID 35406782, 2022). "In this review, we summarize the mechanism of how PTPN22 and its genetic variants are involved in the pathophysiology of autoimmune diseases." (PMID 36013501, 2022). "The single nucleotide polymorphism (SNP) PTPN22 C1858T (rs2476601) in exon 14 is mainly associated with the onset of autoimmune diseases." (PMID 36013501, 2022). "Previously, our team systematically analyzed the association between the PTPN22 polymorphism and autoimmune diseases using the Bayesian approach, then reviewed the immunologic functions of the PTPN22 polymorphism." (PMID 36013501, 2022). "In conclusion, as a susceptibility gene of autoimmune diseases, PTPN22 gene plays an important role in ITP." (PMID 35692826, 2022). "Not only the C1858T polymorphism but other PTPN22 gene variants also have been investigated to be associated with autoimmune disorders." (PMID 36013501, 2022). "The recent exploding numbers of genetic studies have made it possible to find these associations rapidly, and a variety of autoimmune diseases were found to be associated with PTPN22 polymorphisms." (PMID 36013501, 2022).
autoimmune disease (continued). "PTPN22 was first associated with type 1 diabetes mellitus, and it has since demonstrated involvement in the pathogenesis of various autoimmune diseases, such as rheumatoid arthritis." (PMID 36588574, 2022). "To broaden the perspective of this association, in this review, we aim to summarize how the PTPN22 gene and its variants are associated with the onset and progress of a large set of autoimmune diseases." (PMID 36013501, 2022). "In consequence, the Lyp620W variant of PTPN22 was identified in multiple autoimmune diseases, including T1D, RA, systemic lupus erythematosus (SLE), Graves’ disease, and myasthenia gravis." (PMID 35634292, 2022). "Studies have shown that there is a statistical association between the PTPN22 R620W mutation and autoimmune diseases such as rheumatoid arthritis, Type 1 diabetes, Graves' disease, and systemic lupus." (PMID 34805727, 2021). "The fine-mapping analysis largely confirmed the missense variant in PTPN22, thought to be causal in a range of different autoimmune diseases." (PMID 33574239, 2021). "We have previously shown that both anti-CD28 and soluble TNFα inhibited the expression of PTPN22, a gene that is associated with several autoimmune diseases, but only anti-CD28 promoted the production of IL-17A/F in anti-CD3 stimulated PBMCs." (PMID 34301319, 2021). "PTPN22 function affects the responsiveness of T and B cell receptors, and different mutations of PTPN22 have been associated with susceptibility to autoimmune diseases." (PMID 33807700, 2021). "This variant, like the PTPN22 gene, has been associated with susceptibility to the development of autoimmune diseases such as systemic lupus erythematosus, type-1 diabetes mellitus, and rheumatoid arthritis." (PMID 34735462, 2021). "There are several rare genetic variants of PTPN22 in humans that are associated with increased or decreased risk of autoimmune diseases." (PMID 33717184, 2021). "There are multiple non-synonymous SNPs in PTPN22 associated with increased risk or decreased risk of autoimmune diseases." (PMID 33717184, 2021). "A single nucleotide polymorphism (SNP) in PTPN22, rs2476601, is associated with increased risk of Type 1 Diabetes (T1D) and other autoimmune diseases." (PMID 33717184, 2021). "PTPN22 is the most extensively studied phosphatase in relation to autoimmune disease, and polymorphisms in the PTPN22 gene are heavily associated with rheumatological diseases." (PMID 33425916, 2020). "The association of the PTPN22 R620W SNP with various autoimmune diseases suggests a regulatory role of functional PTPN22 for T cell activation in human." (PMID 32047502, 2020). "PTPN22 encodes a lymphoid-specific phosphatase which acts as a negative regulator of T cells and its polymorphisms have been linked to several autoimmune disorders." (PMID 32973676, 2020). "A single nucleotide polymorphism (SNP) in the gene encoding the tyrosine phosphatase PTPN22 (R620W) is associated with multiple human autoimmune diseases, and PTPN22 has been shown to modulate T cell responses, particularly to weak antigens." (PMID 32047502, 2020). "PTPN22 polymorphism has been described as a risk factor for several autoimmune diseases, and healthy carriers have been reported to have more autoreactive B cells compared to non-carriers." (PMID 32678001, 2020). "Here, we provide evidence that the autoimmune disease-associated phosphatase PTPN22 is a regulator of cDC2 homeostasis." (PMID 32194571, 2020). "The intracellular phosphatase PTPN22 is implicated in immune cell signaling and known as a predisposing gene for autoimmune diseases." (PMID 32603365, 2020). "We attempted to synthesize all meta-analyses on genetic associations of the PTPN22 1858 C>T polymorphism with autoimmune diseases and investigated their validity to discover false positive results under Bayesian methods." (PMID 30871019, 2019).